CXCR1 (C-X-C motif chemokine receptor 1)
Diseases named in the same sentence as CXCR1 in open-access papers (continued):
Sharing a sentence is not in itself a finding about the gene and the disease.
ovarian carcinoma (continued). "In our study, pre-treatment with reparixin, a CXCR1/2 inhibitor, reduced CXCL8-induced TRIM46 expression and cancer cell invasion, further implicating the CXCL8-CXCR1/2 axis in ovarian cancer metastasis." (PMID 39937005, 2025). "By designing CXC motif chemokine receptor (CXCR) 1 with CAR construct in NK cells, these CXCR1/CAR-NK cells promoted effective trafficking and peritoneal infiltration into the ovarian cancer microenvironment." (PMID 38726000, 2024). "To characterize the expression profiles of CXCR1 and CXCR2 in the tumor microenvironment of ovarian cancer tumors, we checked IHC staining in the HPA." (PMID 37765018, 2023). "The CXCR1/CXCR2 are the receptors for IL-8, which is over-expressed in ovarian cancer patients both in serum and ascites." (PMID 38248751, 2023). "For example, CXCR2-modified GPC3-CART had improved trafficking in a hepatocellular carcinoma model, while a CXCR1/2-modified CD70-CART enhanced CART trafficking and efficacy in murine GBM, ovarian cancer and pancreatic cancer models." (PMID 35273619, 2022). "The ONCOMINE online database was used to compare the expression of CXCR1/CXCR2 mRNA in normal ovarian and ovarian cancer tissues." (PMID 33829065, 2021). "This induction was impeded by blockage of IL-8 and CXCR1, suggesting that CAFs secrete chemokines, such as IL-8, which, in turn, enhance PDK1 expression in ovarian cancer cells through CXCR1." (PMID 32071289, 2020). "To identify the expression of IL‐8, CXCR1 and CXCR2 in serous ovarian cancer, we collected patients with ovarian cancer from West China Second University Hospital." (PMID 31793192, 2020). "By studying the expression levels of IL‐8, CXCR1 and CXCR2 in different human ovarian cancer cell lines (SKOV3, A2780), we confirmed the expression of IL‐8 and its receptors in all cell lines tested." (PMID 31793192, 2020). "Alternatively, patients with more advanced ovarian cancer (those with lower differentiation, distant metastasis and advanced FIGO stage) had increased tumoral IL‐8, CXCR1 and CXCR2 expression." (PMID 31793192, 2020). "To confirm the expression of CXCR1 and CXCR2 in ovarian cancer cells, we employed immunocytochemistry and found CXCR2 was mainly expressed in the ovarian cancer cells." (PMID 31793192, 2020). "For the present study, we correlated the expression of IL‐8 and its receptors (CXCR1, CXCR2) with clinical measures (staging, tumour grade and overall survival) in patients with ovarian cancer." (PMID 31793192, 2020). "In addition, we found that OC-MQs increased CXCR1 and CXCR2 expression, including in ovarian cancer cells." (PMID 39937005, 2025). "Further, when CXCL8 binds to CXCR1/2, it can activate transforming growth factor beta-activated kinase 1/Nuclear factor-kappa B (TAK1/NFκB) signaling and enhance the migration and invasiveness of ovarian cancer cells." (PMID 37377954, 2023). "Bioinformatics analysis of the expression of the C-X-C motif chemokine receptors (CXCRs) in ovarian cancer indicated higher expression of CXCR3, -4, -7 mRNA and different expression of CXCR1, -2, -3, -4, -7 mRNA in different pathological types of ovarian tumors." (PMID 38248751, 2023). "Furthermore, CXCR-1 and CXCR-2 were also demonstrated to be strongly expressed in ovarian cancer cell lines, and to activate mitogen-activated protein (MAP) kinase via EGFR, contributing to cell migration and proliferation." (PMID 31703453, 2019). "Stimulation of CXCR1/2 chemokine receptors by interleukin-8 has been shown to induce transient phosphorylation of EGFR, leading to the rapid activation of the p44/42 MAPK (also known as ERK1/2) in ovarian cancer cells." (PMID 22848341, 2012). "CXCR1 and CXCR2 were downregulated in ovarian cancer tissues, while CXCR5 and CXCR6 were not significantly different between ovarian cancer and normal tissues." (PMID 33829065, 2021).
ovarian carcinoma (continued). "However, when treated with the Reparixin (inhibitor of IL‐8 receptors CXCR1 and CXCR2), the migration of ovarian cancer cells decreased compared with the control group no matter whether treated or not treated with the IL‐8." (PMID 31793192, 2020).
prostate carcinoma (25 papers, 2008 to 2025). A carcinoma that arises from epithelial cells of the prostate gland. "Beside their elevated expression in PTEN-deficient prostate cancer cells, CXCR1 and CXCR2 are also expressed on vascular endothelial cells, monocytes and fibroblasts." (PMID 24970800, 2014). "Given that functional impairment of PTEN is reported in up to 30% of all primary prostate cancers and that radical RT is a major treatment option for locally advanced high-risk disease, CXCR1/CXCR2-targeted therapeutics may have a significant impact across a large cohort of patients." (PMID 32743555, 2020). "Phase 1 and 2 clinical trials in prostate cancer with Navarixin, a small-molecule inhibitor of CXCR1/2, have been completed." (PMID 40362634, 2025). "Combined, these results confirm that a CXCR1/2-targeted therapeutic approach can drive radiosensitivity in PTEN-depleted prostate cancer models." (PMID 32743555, 2020). "It had been reported in literature that CXCR1 was widely expressed in prostate cancer, bladder cancer, stomach cancer, colon cancer, endometrial cancer and melanoma cancer cells." (PMID 28454081, 2017). "A study conducted by one group suggests that CXCR1/2 receptor/ligand signaling not only induces activation of AKT but also increases the expression of AKT in androgen-independent prostate cancer cell lines." (PMID 23420470, 2013). "Taken together, these results establish the clinical relevance of the PTENLOW/CXCR1/2HIGH cluster in two distinct cohorts and, furthermore, reveal the downstream significance of this biology in locally advanced prostate cancer to adverse outcomes after both surgery and RT interventions." (PMID 32743555, 2020). "Furthermore, loss of PTEN function concurrently increased the expression of CXCL8 receptors (CXCR1 and CXCR2), with the resulting elevated autocrine CXCL8 signaling acting to sustain the viability of these PTEN-deficient prostate cancer cells." (PMID 24970800, 2014). "Interestingly, CXCL8 signaling increased the expression of CXCR1 and CXCR2 receptors in PTEN-deficient prostate cancer cells, suggesting that CXCL8 signaling acts in a self-sustaining capacity, to potentiate its signaling in PTEN-deficient prostate cancer." (PMID 24970800, 2014). "Moreover, the present study indicates that CXCR1/2 antagonist and Src family inhibitors or ß-catenin inhibitors may be promising pharmacological approaches in the treatment of advanced prostate carcinoma." (PMID 31500632, 2019). "Further studies found that inhibition of CXCL8 and its receptor chemokines CXCR1 and CXCR2 promote G1 cell cycle arrest and apoptosis, suggesting that CXCR1 and CXCR2 inhibit tumor progression in prostate cancer by influencing cell proliferation." (PMID 41347146, 2025). "McClelland and colleagues have summarized numerous inhibitors developed to target IL-8 or its receptor CXCR1/2 for the treatment of chronic obstructive pulmonary disease (COPD), asthma, diabetes, pneumonia, and solid tumors, including prostate cancer." (PMID 40362634, 2025). "This review explores the role of interleukin-8 (IL-8) and its receptors, CXCR1 and CXCR2, in prostate cancer." (PMID 39199570, 2024). "This review delves into the intricate roles of interleukin-8 (IL-8) and its receptors, CXCR1 and CXCR2, in prostate cancer (PCa), particularly in castration-resistant (CRPC) and metastatic CRPC (mCRPC)." (PMID 39199570, 2024). "Recently, several chemokines, including CXCL8 and its receptors (CXCR1 and CXCR2), have been shown to impact the development and progression of prostate cancer." (PMID 39766038, 2024). "Chronic hypoxia elevated the expression of CXCR1 and CXCR2 in prostate cancer cells and then CXCRs promoted the secretion of IL-8." (PMID 36452497, 2022). "Nagaya and co-workers identified higher expression of the CXC chemokine signaling genes, including CXCL1, CXCL3, CXCL6, CXCR1 and CXCR2 in prostate cancer bone metastases." (PMID 35328625, 2022).
prostate carcinoma (continued). "Using animal models and human tissue samples, the authors show here that ASC recruitment to prostate cancers is mediated by the chemokine CXCL1, which is secreted from tumour cells, and acts on CXCR1 on ASCs." (PMID 27241286, 2016). "Our prior studies demonstrated that silencing of PTEN expression increased the transcription and secretion of CXCL8 and increased gene expression of the receptors CXCR1 and CXCR2 in prostate cancer cells." (PMID 24970800, 2014). "In addition, activation of both CXCR1 and CXCR2 increases the rate of cell proliferation in prostate cancer." (PMID 27682863, 2016). "Immunofluorescence analysis of tissues from prostate cancer patients demonstrated the presence of cells with strong CXCR1 expression in the tumour stroma of some, but not all patients." (PMID 27241286, 2016). "CXCR1 and CXCR2 could stimulate prostate cancer progression through autocrine signaling of cancer cells." (PMID 25990390, 2015). "Moreover, we have confirmed that exposure to 5-FU potentiates this level of CXCL8 signaling by concurrently inducing CXCL8 secretion and up-regulating CXCR1 and CXCR2 gene expression in metastatic prostate cancer cells." (PMID 22590561, 2012). "SX-682, another CXCR1/2 inhibitor is being investigated in pancreatic ductal adenocarcinoma (PDAC) and metastatic melanoma (NCT04477343 and NCT03161431), whereas the selective CXCR2 inhibitor AZD5069 is being evaluated in metastatic castration-resistant prostate cancer (NCT03177187)." (PMID 35504900, 2022). "Similarly, an ongoing stage 2 clinical trial (NCT03473925) on advanced microsatellite-stable CRC, castration-resistant prostate cancer, and NSCLC is investigating NET formation during combination therapy with a CXCR1/2 antagonist (navarixin) and PD1 inhibitor (pembrolizumab)." (PMID 35504900, 2022). "We validated the efficacy of the CXCR1/2-targeted pepducin, x1/2pal-i3, to attenuate CXCL-mediated tumourigenicity in PTEN-modulated prostate cancer cells, using an appropriate non-targeting peptide as the relevant control." (PMID 32743555, 2020).
colon cancer (24 papers, 2004 to 2025). "CXCR1, a receptor for IL-8, constitutes the primary mechanism of neutrophil recruitment, and its overexpression is observed in colon tissue during UC, which may increase the risk of colon cancer." (PMID 35620404, 2022). "Previous research reports have shown that the combination of CXCL8 receptors CXCR1/2 promotes the progression of colon cancer and liver metastases." (PMID 35922850, 2022). "Our results showed that the expression of LSECtin was closely related to the activation of CXCL8/CXCR1/2 signal axis in colon cancer." (PMID 36358719, 2022). "Data from vitro and clinical studies also suggested that the activation of CXCL8/CXCR1/2 signal axis is an important factor in regulating the immune microenvironment of colon cancer and leading to less benefit of ICIs treatment in colon cancer." (PMID 36358719, 2022). "The use of CXCR1/2 oral inhibitors leads to the inhibition of metastasis to the liver of colon cancer due to the inhibition of neovascularization and increased apoptosis of tumor cells." (PMID 33925224, 2021). "Although CXCR1 and CXCRs have a considerable structural similarity, the proliferation and angiogenesis of human colon cancer cells probably depends on IL-8 binding only to CXCRs." (PMID 27557518, 2016). "We observed a significantly higher level of CXCR1 epithelial expression in rectal cancer tissue compared with colon, with 18.6% of rectal tumour cases showing strong expression compared with 7.3% of colon cancer cases (P=0.033)." (PMID 21285972, 2011). "Moreover, our previous studies and existing evidence suggested that CXCL8/CXCR1/2 is an important signal to promote liver metastasis of colon cancer." (PMID 36358719, 2022). "Therefore, CXCL8/CXCR1/2 signal may regulate the expression of LSECtin and play an important role in the immune microenvironment regulation in colon cancer." (PMID 36358719, 2022). "Emerging clinical evidence suggests that CXCL8/CXCR1/2 signal axis plays a key role in immune escape and CXCL8 high expressed colon cancer seldom benefit from ICIs therapy." (PMID 36358719, 2022). "It has been reported that targeting CXCR1 and CXCR2 using orally active small-molecule antagonist, SCH 527123, potentially inhibits human colon cancer liver metastasis and also sensitizes cells to oxaliplatin." (PMID 28484461, 2017). "It has been reported that blockade of CXCR1 and CXCR2 using SCH 527123 antagonist potentially inhibits human colon cancer liver metastasis and also sensitizes cells to oxaliplatin." (PMID 28484461, 2017). "In a preclinical human colon cancer cell growth and metastasis model in nude mice, orally active CXCR2/CXCR1 antagonists partially decreased liver metastasis by reducing tumor neovascularization through CXCR2 signaling." (PMID 26104296, 2015). "The CXCL8/CXCR1/2 chemokine axis and PI3K/AKT signaling pathway mediated EMT progress might well be a critical mechanism of colon cancer liver metastasis." (PMID 35922850, 2022). "Interestingly, expression of CXCR1 and CXCR2 has been shown to be elevated in colon tumor epithelium relative to normal adjacent tissue (P < 0.001)." (PMID 30820706, 2019). "Moreover, other studies show that expression of IL-8 can induce migration and recruitment of CXCR1 (+) CD8 (+) T cells in inflammatory areas and using the Leptin trigger of the mouse model of colon cancer can promote the recruitment of T cells and enhance immune response." (PMID 36532065, 2022). "In practice, several experimental evidences have documented that high expression of CXCL8 binds to receptors CXCR1 and CXCR2, mediates the transcriptional process of PI3K/Akt/mTOR signaling cascade, and promotes metastasis in multiple malignant tumors, specifically in colon cancer." (PMID 35922850, 2022). "However, whether blocking CXCL8/CXCR1/2 signal or LAG3/LSECtin can increase the efficacy of anti-PD-1/PD-L1 or anti-CTLA4 in patients with colon cancer is still lack of effective experimental verification." (PMID 36358719, 2022).
COVID-19 (20 papers, 2021 to 2025). A disease caused by infection with severe acute respiratory syndrome coronavirus 2. "For instance, CXCR1 inhibitors and IL-17 blockers, previously explored in COVID-19, offer valuable insights into potential interventions for modulating immune responses." (PMID 40124360, 2025). "Here, we show that anti–IL-8 antibodies and targeted inhibition of IL-8 signaling by the CXCR-1/-2 blocker reparixin reduced neutrophil activation, degranulation and NET formation caused by COVID-19 plasma." (PMID 34403366, 2021). "BMS-986253 is a monoclonal anti-CXCL-8 antibody and is currently being studied for its potential impact on COVID-19 Similarly, reparixin, a CXCR1 and CXCR2 receptor antagonist, is currently in clinical trials for its use in COVID-19." (PMID 34421600, 2021). "Furthermore, COVID-derived PBMCs and monocytes had upregulated expression of migration markers, including endothelial adhesion molecules, including L-selectin and intercellular adhesion molecule 1 (ICAM1), and CC/CXC chemokine receptors (CCR1, CXCR1), as a function of the severity of COVID-19." (PMID 37310504, 2023). "These four inflammatory markers were mainly expressed by neutrophils, which have a high expression of the CXCL8 receptors CXCR1 and CXCR2, which showed a significant increase in both KD and severe COVID-19 when compared with the respective controls." (PMID 36159873, 2022). "Our results suggest that increased CXCR1, CXCR2, Mac-1/CD11b and L-selectin on CD16+ monocytes contribute to the immunopathogenesis of severe COVID-19 by increasing transmigration of these monocytes into tissues, including the lung." (PMID 34108966, 2021). "Cytokine-related genes that were found to be dysregulated in both CAD patients and COVID-19 patients include chemokines (CCL3 and CCL4), chemokine receptor CXCR1, and a TNFSF gene, LTB." (PMID 34071557, 2021). "Lung cells from COVID-19 patients show expression of HIF1α, TLR2, TLR4, PFKFB3, CXCR1, −2 and −4, SOD2, PLAUR and other genes expressed in immature myeloid cells." (PMID 33345622, 2021). "Although most blood neutrophils stained positive for CXCR1 and CXCR2, the relative expression levels of these chemoattractant receptors were significantly lower on blood neutrophils from patients with COVID-19 compared with blood neutrophils from healthy controls." (PMID 34793331, 2022). "In addition, we found that CD16+ monocytes from people with severe COVID-19 had upregulated CXCL8 receptor genes, CXCR1 and CXCR2, compared to mild cases." (PMID 34108966, 2021). "Furthermore, upon bacterial challenge, a similar pattern of cell surface receptor phenotype with reduced expression of CXCR1, CXCR2, CXCR3, CCR1, CCR5 and the maturation marker CD15, with increased expression of CXCR4 and CD66b was found in neutrophils from acute-phase COVID-19 patients." (PMID 35007290, 2022).
pancreatic cancer (20 papers, 2012 to 2025). "IL8 in association with CXCR1 was related to a high prognosis of human pancreatic cancer." (PMID 30326660, 2018). "Therapeutic strategies to target the CXCR-1/CXCR-2 axis or combination with immunotherapy have been proposed to improve antitumor efficacy in pancreatic cancer, metastatic melanoma, and metastatic colorectal carcinoma." (PMID 38358826, 2024). "In pancreatic cancer a positive correlation was found between CXCR1 and both CD44 and CD133 stemness marker expression." (PMID 30788286, 2019). "Targeting myeloid cell CXCR1/2 enhances antitumor immunity in pancreatic cancer." (PMID 40362634, 2025). "Interestingly, we found that both pancreatic cancer cells and PSCs expressed IL-8 receptors CXCR1 and CXCR2 implicating the possibility that G9a-increased IL-8 could affect cancer cells and PSCs simultaneously." (PMID 27531902, 2016). "SB225002, a selective CXCR2 antagonist, and SCH-527123, a CXCR1/CXCR2 antagonist, attenuated the effects of conditioned media of senescent hPSCs on the proliferation and migration of pancreatic cancer cells." (PMID 36012531, 2022). "Exogenous CXCL8 added to pancreatic cancer cells in vitro increased their invasion ability, tumorsphere formation, and CSC population and addition of a CXCR1-blocking monoclonal antibody was able to revert all these effects." (PMID 30788286, 2019). "Some researchers took advantage of tumor-produced IL-8 in order to guide the IL-8 receptor (CXCR1 or CXCR2)-expressing CAR-T cells to infiltrate solid tumors (glioblastoma, hepatocellular carcinoma (HCC), ovarian and pancreatic cancer), and stimulate an antitumor immune response." (PMID 35211124, 2022). "engineered interleukin 8 (IL‐8) receptors CXCR1 or CXCR2 in αvβ6‐targeted CAR T‐cells and demonstrated the superior anti‐tumour activity of these armed CAR‐T cells against established αvβ6‐expressing ovarian or pancreatic tumour xenografts." (PMID 36495108, 2022).